USP11 (ubiquitin specific peptidase 11)
Diseases named in the same sentence as USP11 in open-access papers (continued):
Sharing a sentence is not in itself a finding about the gene and the disease.
acute lymphoblastic leukemia (1 paper, 2024). Leukemia with an acute onset, characterized by the presence of lymphoblasts in the bone marrow and the peripheral blood. "Our findings reveal a novel feedback loop regulation between NOTCH1 and USP11, underline the role of active deubiquitination in cancer, and provide a rationale for therapeutic targeting of USP11 in acute lymphoblastic leukemia." (PMID 38007584, 2024). "Here, we identified a regulatory feedback loop between NOTCH1 and the USP11 deubiquitinase in T-cell acute lymphoblastic leukemia (T-ALL)." (PMID 38007584, 2024).
alcoholic fatty liver disease (1 paper, 2021). Lipid infiltration of the hepatic parenchymal cells that is due to alcohol abuse. "Finally, elevated USP11 and reduced KLF4 levels were detected both in a hepatic steatosis in vitro model and in public clinical data of non‐alcoholic fatty liver disease and HCC patients." (PMID 34114341, 2021).
Anxiety (1 paper, 2025). Intense feelings of nervousness, tension, or panic often arise in response to interpersonal stresses. "USP11 silencing was found to improve walking behavior, anxiety-like behavior, and working memory in R6/1 mice." (PMID 39780069, 2025).
atherosclerosis (1 paper, 2025). A disease characterized by the build-up of fatty material and calcium deposition in the arterial wall resulting in partial or complete occlusion of the arterial lumen. "CD36 undergoes ubiquitination and covalent attachment of both K48 and K63 polyubiquitin chains; CD36-ubiquitin cleavage by deubiquitinases such as UCHL1 or USP11 modulates foam cell formation and atherosclerosis-linked outcomes." (PMID 40563926, 2025). "Targeting CD36, UCHL1 or USP11 using small molecule inhibitors or reverse genetic strategies could provide new strategies to target both atherosclerosis and cancer." (PMID 40563926, 2025).
Azoospermia (1 paper, 2024). Absence of any measurable level of sperm,whereby spermatozoa cannot be observed even after centrifugation of the semen pellet. "In this study, we explored the expression, function, and mechanism of USP11 in controlling the proliferation and apoptosis of human SSCs as well as the association between its abnormality and azoospermia." (PMID 38722330, 2024).
bronchiectasis (1 paper, 2023). Segmental, irreversible dilation of the bronchial tree resulting in the accumulation of secretions which leads to obstruction. "This concept was validated using a sub-library of scFvs selected against two human enzymes: Cyclin-Dependent Kinase 2A (CDK2A), a human protein important in cancer biology, and Ubiquitin Specific Peptidase 11 (USP11), which is associated with bronchiectasis." (PMID 36827414, 2023).
coronary heart disease (1 paper, 2024). "We identified eight hub genes (CIRBP, USP7, ELAVL1, ATG13, ALOXE3, PRKAA2, USP11, SLC38A1) that exhibited significant differences between coronary heart disease (CAD) patients and healthy controls." (PMID 39610972, 2024).
esophageal squamous cell carcinoma (1 paper, 2024). Esophageal squamous cell carcinoma (ESCC) is a type of esophageal carcinoma (EC) that can affect any part of the esophagus, but is usually located in the upper or middle third. "This dataset involved RNA sequencing of KYSE410 cells, a human esophageal squamous cell carcinoma cell line, in which USP11 was knocked down." (PMID 39617751, 2024).
fibrosis (1 paper, 2025). the formation of excess fibrous connective tissue in an organ or tissue in a reparative or reactive process. "The clinical relevance of the USP11 inhibitor and its effect on preventing PF were investigated in a TGF-β-induced fibrosis in AOs and bleomycin (BLM)-induced mouse model." (PMID 40225577, 2025).
inflammatory bowel disease (1 paper, 2016). A spectrum of small and large bowel inflammatory diseases of unknown etiology. "The anti-inflammatory effect of USP11 inhibitor may be beneficial to other diseases including inflammatory bowel disease." (PMID 27448760, 2016).
intervertebral disc degeneration (1 paper, 2024). "Very recently, SIRT3 stabilization by deubiquitinase USP11 was found to significantly ameliorate oxidative stress-induced ferroptosis in intervertebral disc degeneration, suggesting an important role of SIRT3 in mitigating ferroptosis during disease." (PMID 38395990, 2024).
liver cancer (1 paper, 2019). An epithelial or non-epithelial malignant neoplasm that arises from the liver. "Nevertheless, USP11 functions as an oncogene in liver cancer to promote growth and metastasis." (PMID 31592114, 2019).
liver dysfunction (1 paper, 2021). "In summary, this is the first study describing USP11 as a modulator of KLF4 in liver dysfunction." (PMID 34114341, 2021).
metastatic melanoma (1 paper, 2011). A melanoma that has spread from its primary site to another anatomic site. "The expression of three out of four analyzed genes (USP10, USP11, USP22) was significantly higher in metastatic melanoma compared with benign nevi and primitive tumors, suggesting that their expression is associated with a more aggressive and invasive phenotype." (PMID 21283576, 2011).
osteosarcoma (1 paper, 2022). A usually aggressive malignant bone-forming mesenchymal neoplasm, predominantly affecting adolescents and young adults. "Targeting USP11 as a therapeutic strategy for osteosarcoma is feasible and more experiments are needed to further verification." (PMID 35715413, 2022). "The critical value of USP11 in the occurrence and progression of osteosarcoma has been identified via its deubiquitylation and stabilization of RAE1." (PMID 35715413, 2022).
pancreatic ductal adenocarcinoma (1 paper, 2024). An infiltrating adenocarcinoma that arises from the epithelial cells of the pancreas. "In addition, research has revealed that mitoxantrone can inhibit USP11 and affect the survival of pancreatic ductal adenocarcinoma cells." (PMID 38531846, 2024).
pneumonia (1 paper, 2024). An acute, acute and chronic, or chronic inflammation focally or diffusely affecting the lung parenchyma, caused by an infection in one or both of the lungs (by bacteria, viruses, fungi, or mycoplasma.). "USP11 exacerbates pneumonia by deubiquitinating and stabilizing LPA1, a proinflammatory factor, enhancing LPA1-mediated proinflammatory effects." (PMID 38322269, 2024). "Several studies have reported that USP11 and USP14 contribute to the aggravation of inflammation in LPS-induced pneumonia." (PMID 38322269, 2024).
renal clear cell carcinoma (1 paper, 2022). "Therefore, USP11 can be used as a tumor suppressor in renal clear cell carcinoma." (PMID 35359344, 2022).
Sepsis (1 paper, 2025). Sepsis is defined as life-threatening organ dysfunction caused by a dysregulated host response to infection. "USP11 inhibition by mitoxantrone ameliorated sepsis-associated AKI by downregulating TGFBR2/Smad3 signaling." (PMID 40656894, 2025). "Herein, we hypothesize that inhibiting USP11 activity could regulate TGFBR2 in sepsis and provide protection against sepsis-associated AKI." (PMID 40656894, 2025). "In this study, we evaluated the effects of USP11 inhibition on sepsis-associated AKI." (PMID 40656894, 2025). "We found that inhibiting USP11 ameliorated sepsis-associated AKI by regulating TGFBR2, suggesting that USP11 could be a potential therapeutic target for AKI." (PMID 40656894, 2025). "CLP-induced sepsis upregulates USP11 and TGFBR2, leading to inflammation, oxidative stress, and renal damage." (PMID 40656894, 2025). "The present study reveals that USP11 is a key regulator of sepsis-induced AKI through modulation of the TGFBR2/Smad3 pathway." (PMID 40656894, 2025). "Collectively, these results demonstrate that USP11 may have an important role in sepsis-associated AKI and that inhibiting USP11 may be a promising strategy for the treatment of sepsis-associated AKI." (PMID 40656894, 2025).
small cell lung carcinoma (1 paper, 2024). Small cell lung cancer (SCLC) is a highly aggressive malignant neoplasm, accounting for 10-15% of lung cancer cases, characterized byrapid growth, and early metastasis. "Its interaction promotes the recruitment of deubiquitinase ubiquitin-specific protease 11 (USP11), which inhibits CD133 polyubiquitination and its proteasomal degradation in small cell lung cancer (SCLC)." (PMID 37922108, 2024).
steatosis (1 paper, 2021). Increased lipid within the cytoplasm of cells. "We observed that KLF4 expression dramatically decreased while USP11 increased in in vitro steatosis conditions induced by FFA treatment." (PMID 34114341, 2021). "Importantly, lipid content was reduced and genes involved in fatty acid metabolism were down‐regulated in an in vitro steatosis conditions upon USP11 knockout." (PMID 34114341, 2021).
Xeroderma pigmentosum complementation group C (1 paper, 2017). "Here we show that ubiquitin-specific peptidase 11 (USP11) positively regulates NER by deubiquitinating xeroderma pigmentosum complementation group C (XPC) and promoting its retention at the DNA damage sites." (PMID 29228550, 2017).
cancer (49 papers, 2011 to 2025). A tumor composed of atypical neoplastic, often pleomorphic cells that invade other tissues. "Since USP11 is associated with diseases such as cancer and neurodegeneration, the discovery of inhibitors is an emergent area to provide therapeutic potentials." (PMID 41207628, 2025). "Specifically, gene set enrichment analysis indicated significant enrichment of EGFR- and cancer-associated pathways in USP11-upregulated CRC samples, highlighting USP11’s involvement in EGFR signaling." (PMID 41419456, 2025). "Gene sets related to EGFR signaling were notably enriched in patients with elevated USP11 expression, along with ten other gene sets associated with cancer-related modules." (PMID 41419456, 2025). "Survival data from the pediatric cancer genome project (PeCan) coupled with the expression levels of 52 USP family members showed that USP11 levels are associated with poor prognosis." (PMID 38007584, 2024). "USP11 overexpression is widespread in tumors and has been identified as a diagnostic or prognostic marker for certain cancers." (PMID 37414755, 2023). "Although USP11 has relatively less cleavage activity to lys48-linked ubiquitin chain, it is also identified to regulate the occurrence and progression of several cancers via stabilizing protein expression, which depends on lys48-linked cleavage." (PMID 35715413, 2022). "As a deubiquitinase, USP11 interacts with multiple substrate proteins linked to cancer-related pathways." (PMID 36385557, 2022). "We demonstrate that USP11 plays an oncogenic role in lymphoid malignancy and controls LCK activity in association with USP7 via LCK deubiquitination." (PMID 36490346, 2022). "In contrast, USP11 is highly associated with tumorigenesis in other cancer types such as breast, ovarian, colorectal, pancreatic cancer, melanoma, glioma and squamous cell carcinoma, due to its effect on different signalling pathways." (PMID 34114341, 2021). "In the current study, we provided critical evidence about the association between USP11 and EGFR or TLR signals in CRC; first, the high expression of USP11 in CRC tissues and its association with cancer-related gene sets suggest that USP11 plays an essential role in CRC development." (PMID 41419456, 2025). "Therefore, the diagnostic and prognostic value of USP11 in cancer patient needs to be further developed." (PMID 35359344, 2022). "USP11, which is an X-linked retinal disorder gene, regulates several cellular functions, including histone regulation, NF-κB signaling, DNA repair, and viral infection, and is associated with multiple types of cancers." (PMID 33919439, 2021). "As aberrant ERG expression collaborates with Pten haplo-insufficiency to promote cancer progression, we assessed whether USP11 loss would affect ERG-dependent cellular processes." (PMID 30733438, 2019). "USP11, a crucial member of the USPs family, emerges as a promising target for cancer therapy through inhibitor development." (PMID 41207628, 2025). "For example, a compound called demethylenebernerine (DMB) has been shown to bind to deubiquitinase ubiquitin-specific peptidase 11 (USP11), which has been shown to regulate progression and chemoresistance of colorectal, breast, ovarian and other human cancers." (PMID 40277903, 2025). "USP11, a USP-family member implicated in cancer and neurodegeneration, carries an atypical catalytic domain which is split into two segments through the insertion of a UBL2 domain and an intrinsically disordered region (IDR)." (PMID 41207628, 2025). "Among these, USP11 has garnered attention due to its structural similarity with cancer-related USPs (USP4 and USP15) and its elevated expression in CRC tissues, and its role in facilitating CRC progression, including proliferation and metastasis." (PMID 41419456, 2025).
cancer (continued). "Hematoxylin and eosin (H&E) staining results represented that tumor tissues derived from Ctrl HCT-15-xenografted NSG mice showed a dense population of cancer cells as compared to those of USP11-KO HCT-15 xenografted NSG mice." (PMID 41419456, 2025). "RNA sequencing data identified USP11 upregulation in CRC tissues and found it to be associated with cancer-related gene sets, particularly those related to EGFR and TLR signaling." (PMID 41419456, 2025). "Deubiquitinase ubiquitin‐specific protease 11 (USP11) belongs to the deubiquitinating family and has previously been reported to play a critical role in cancer pathogenesis." (PMID 38229475, 2024). "The findings that USP11 stimulates tumorigenesis have been exclusively obtained from artificial overexpression or knockdown of USP11 in various cancer cell lines, in which multiple oncogenic proteins have been identified as its substrates." (PMID 39270819, 2024). "Together, these clinical findings are consistent with our results in mice, suggesting an opportunity to use murine systems to further explore how USP11 regulates E-cadherin to control human breast biology as well as cancer development and progression." (PMID 39270819, 2024). "Elevated USP11 expression promotes cancer cell proliferation by inhibiting ferroptosis through deubiquitination and stabilization of Nrf2 in NSCLC cells." (PMID 38072908, 2023). "Cancer patient survival analyses have indicated the clinical relevance of downregulated USP11 expression, with individuals having higher USP11 expression experiencing a more favorable clinical outcome." (PMID 38139829, 2023). "In this review, we mainly describe the biological functions and behaviors of USP11, as well as its role in different cancers." (PMID 35359344, 2022). "We initially summarize the role of USP11 in different cancers and further discuss the possibility of USP11 as a therapeutic strategy." (PMID 35715413, 2022). "In one way, HPV-16E7 can degrade pRb, which is a typical tumor suppressor gene, so USP11 exhibits cancer-promoting property in the pathway." (PMID 35359344, 2022). "Since USP11 plays an important role in the occurrence and development of a variety of cancers, it can be used as a potential therapeutic target to treat cancer." (PMID 35359344, 2022). "Some scholars have found that cellular IAP2 (cIAP2) are stable in a variety of cancer cells, and its stability is regulated by USP11." (PMID 35359344, 2022). "The balance between USP11 and other ubiquitinase maintain the expression and activation status of critical proteins of cancer-related signaling pathways." (PMID 35715413, 2022). "Due to the dual role of USP11 in cancer, not only more specific targeted drugs for USP11 need to be developed, but also upstream proteins controlling USP11 expression need to be explored creatively." (PMID 35359344, 2022). "When the upstream protein of USP11 is well studied, we can regulate its expression by regulating its upstream, which will bring revolutionary changes to the treatment of cancers related to USP11." (PMID 35359344, 2022). "Oncogenic functions of USP11 have been studied in cancer, both in solid tumors by controlling of DNA damage response, regulation of tumor suppressors, and apoptosis and in blood tumors via the control of protein synthesis." (PMID 36490346, 2022). "All above results demonstrate that USP11 is related to the occurrence and progression of multiple cancers, targeting USP11 or using ono-specific USP11 inhibitor mitoxantrone is a feasible and effective therapeutic approach for various cancer treatment." (PMID 35715413, 2022). "There are still some proteins that interact with USP11 that are not described in this section, and they are mentioned in the relationship between USP11 and cancer." (PMID 35359344, 2022).